MMP9 (matrix metallopeptidase 9)
Diseases named in the same sentence as MMP9 in open-access papers (continued):
Sharing a sentence is not in itself a finding about the gene and the disease.
tumor (continued). "Among the bioactive compounds identified, specific peptides from the cyanobacterium Lyngbya majuscula, such as Isomalyngamide A and A-1, have demonstrated particularly potent anticancer properties by inhibiting VEGFR2 and MMP-9, which are critical factors in tumor growth and metastasis." (PMID 39195454, 2024). "Therefore, the role of MMP-2 and MMP-9 is considered to be one of the key steps in tumor metastasis." (PMID 38776295, 2024). "Interestingly, MMP9, a protease crucial for tumor cell invasion into neighboring tissues and distal metastasis, is expressed in both CAFs and cancer cells but only in 3D co-cultures, highlighting the importance of CAF/cancer cell crosstalk for MMP9 secretion." (PMID 39700125, 2024). "Particularly MMP-2 and MMP-9 are well known for promoting tumor migration and invasion." (PMID 38539165, 2024). "Bone marrow-derived, MMP-9-expressing macrophages also participate in tumor neovascularization together with vascular endothelial progenitor cells, providing an additional mechanism for tumor angiogenesis." (PMID 38580870, 2024). "The antimetastatic actions of amentoflavone by inhibition of MMPs, especially MMP-2 and MMP-9, have been believed to be involved in tumor progression, partly because of their ability to degrade collagen type IV, one of the major components of basement membranes." (PMID 38672151, 2024). "The IFN-γ pathway was activated in MICA+ tumor cells and MMP9+ macrophages." (PMID 38254761, 2024). "Moreover, immunohistochemical staining of the tumor tissue was performed, compared with the control group, the expressions of Ki-67, MMP9, and EGFR in the myricetin treatment group were significantly decreased." (PMID 38026996, 2023). "In addition, a cooperative effect of MMP-2 and MMP-9 was demonstrated in an experimental in vivo model, which enhanced the angiogenic phenotype and invasiveness of tumor keratinocytes." (PMID 36674806, 2023). "However, more substantial differences in the expression levels of some genes (ICAM-1, MMP-2, MMP-9, IL-6, and CX-43) were observed, indicating the potential influence of the cancer cell type on secondary tumor progression." (PMID 38001146, 2023). "In addition, in breast cancer patients, chronic inflammation can upregulate the expression of MMPs (such as MMP-2 and MMP-9), thus promoting tumour angiogenesis, tumour occurrence, and metastasis." (PMID 37742025, 2023). "Considering that growth of tumour cells in vivo occurs in a three‐dimensional environment, 3D cell culture showed that the LCN2/LOXL2/MMP9 ternary complex degraded the extracellular matrix by promoting the formation and extension of filopodia, thereby enhancing the invasion of tumour cells." (PMID 37753805, 2023). "In addition, MDSCs promote tumor progression through the induction of MMP-9 and TGF-β, which are responsible for the establishment of a more invasive tumor phenotype." (PMID 37371856, 2023). "MMP-2 and MMP-9, among all MMP members, have been linked to tumor metastasis." (PMID 36785788, 2023). "The decrease of VEGF and MMP-9 can promote the normalization of tumor blood vessels, restore the normal function of vascular endothelial, and facilitate the transport, adhesion, and infiltration of T cells to tumor tissues." (PMID 36759928, 2023). "For example, in cancer, CLU enhances MMP9 activation in macrophages and breast cancer cells, which may contribute to the tissue reorganization into the tumor by serving as a modulator for ECM degradation and by promoting invasion of cancer cells." (PMID 37685987, 2023). "To investigate the underlying mechanism, we evaluated several tumor growth and migration markers by western blot, specifically Bcl-2 and p21, modulators of apoptosis and cancer progression, respectively, and metalloproteinase-2 (MMP2) and -9 (MMP9), related with tumor invasion ability." (PMID 36800968, 2023). "Hence, MMP-9 can be used as a prognostic indicator in assessing tumor staging and nodal involvement." (PMID 36938194, 2023).
tumor (continued). "In addition to these functions, MMP9 is also known to promote the formation of new lymphatic vessels, which potentiates further metastases of the tumor cells." (PMID 36756017, 2023). "Moreover, MMP9 is highly expressed in various tumor tissues and promotes the progression of tumor cells." (PMID 37239383, 2023). "Moreover, it will also induce the production of CCL4 and MMP9 with this immune cell type, leading to the promotion of lymph angiogenesis and the remodeling of the tumor stroma." (PMID 36672343, 2023). "In addition to promoting tumor growth by secreting MMP-9 and TNF, NTLS-DCs further inhibit CD8+ T-cell activity by the L-arginine pathway and trigger Treg responses by secreting TGF-." (PMID 37842234, 2023). "Tumor invasion and metastasis are significantly influenced by MMP-9." (PMID 37509493, 2023). "The analysis of tumor tissue lysates from patients who had neoadjuvant therapy revealed that there was an increase in the expression of pro-angiogenic proteins [Matrix metallopeptidase (MMP9), MMP8, and IL-8] in tumors with a greater level of MDSCs." (PMID 37842234, 2023). "Similar to MMP2, MMP9 plays a major role in tumor angiogenesis." (PMID 37946098, 2023). "Here, PKD3 is required for the secretion of tumor promoting factors such as MMP9, IL-6 and IL-8." (PMID 37293129, 2023). "Moreover, cell-free LGG supernatant decreased matrix metallopeptidase 9 (MMP-9) levels and tumor-invasiveness in several CRC cells." (PMID 36918929, 2023). "Combined, these explorative experiments might hint at a radiogenic upregulation of auto-/paracrine TGF-β1 signaling and a TRAM-34-sensitive MMP-9-mediated remodeling of the tumor microenvironment." (PMID 37996600, 2023). "MMP9, which is involved in the degradation of the tumor extracellular matrix, is a mediating factor with regard to the local invasion and distant metastasis of tumor cells." (PMID 36768253, 2023). "Indeed, a significantly higher expression of MMP-9 has been shown in tumours with invasive T3 and T4 stages compared to T1 and T2 tumours." (PMID 38203696, 2023). "MDSCs along with tumor associated macrophages (TAMs) also play an important role in angiogenesis: secretion of VEGF, platelet-derived growth factor (PDGF), and matrix metalloproteinase-9 (MMP-9) by TAMs and MDSCs leads to increased tumor vasculature, providing nutrients for tumor growth." (PMID 36768686, 2023). "This was due to the induction of MMP-9 expression in BMSCs after contact with tumor cells." (PMID 36674806, 2023). "Because of its biological role, MMP9 is involved in tumor cell invasion and cancer cell metastasis." (PMID 36793711, 2023). "MMP2 and MMP9 (two gelatinases that are members of the matrix metalloproteinase family) can facilitate malignant cell progression and promote tumor growth, invasion, and metastasis owing to their ability to degrade type IV collagen in the extracellular matrix and basement membrane 21,22." (PMID 36778127, 2023). "One mechanism by which MMP-2 and MMP-9 activity induce cancer angiogenesis involves the cleavage of latent TGF-β in a CD44-dependent manner that may promote tumor growth and invasion." (PMID 36674806, 2023). "The EMT status may be related to MMP9 changing the tumor immune microenvironment through dendritic cells and macrophages." (PMID 36911370, 2023). "Neutrophils could secrete immunosuppressive mediators, including ROS, chemokines, and MMP-9, which contributed to a pro-tumor microenvironment." (PMID 37334354, 2023). "MMP9 upregulation was more pronounced in large tumors as compared to small tumors, suggesting a positive correlation between lung MMP9 protein expression level and tumor size." (PMID 37903851, 2023). "In addition, the phenomenon of TAM inhibition by adiponectin synergizes with the downregulation of VEGF and MMP-9 expression in tumor tissue." (PMID 37686525, 2023).
tumor (continued). "In the present experiments, the increased expression of VEGF, COX-2, MMP2, and MMP9 protein in the liver tissue of mice with CRC liver metastasis after SHP-2 knockout revealed that the deletion of SHP-2 may promote the tumor micro-angiogenesis." (PMID 37304233, 2023). "Subsequently, the expression of markers such as CD31 and MMP9 were used to indicate the extent of tumor angiogenesis and metastasis, respectively, and the CPPS-II + DOX group significantly downregulated the expression of CD31 and MMP9 in the tumor tissues and reduced the migration ability of tumors." (PMID 37375842, 2023). "Our study showed that BAE, BAI, and WOG could inhibit the activities of MMP-2 and MMP-9, which reasonably explains the inhibitory effect of S. baicalensis on tumor invasion and metastasis." (PMID 38232757, 2023). "Moreover, there was a positive correlation between the degree of tumor infiltration and the level of MMP-9 activation." (PMID 38089632, 2023). "Therefore, it is suggested that when performing surgical resection, it is necessary to expand the range of tumor resection for patients with ruptured FC identified by the levels of serum MMP-9 and MMP-2." (PMID 36918768, 2023). "Importantly, TIMP3 binds to MMP2 and MMP9, and we have previously reported that GBM MMP2 is expressed by tumor cells whereas MMP9 is expressed by tumor-infiltrative neutrophils." (PMID 37511403, 2023). "The tumor-suppressive role of the KISS1R was mainly linked to the inhibition of tumor invasion via the suppression of nuclear factor kappa-B (NF-κB) activity and expression of MMP-9 and by inhibiting mitogen-activated protein kinase (MAPK) and ERK pathways." (PMID 37640761, 2023). "Moreover, knockdown of PKD3 in prostate cancer cells inhibited the secretion of tumor-promoting factors amongst them MMP-9, IL-6, Il-8 and GROα." (PMID 37293129, 2023). "On the other hand, it was also remarkable that we found high expressions of several factors by ECs from non-tumor areas from prostatectomies (MMP-9 and 11, and TIMP-3) compared with these same cell types from previous benign biopsies in the zone where the tumor arose." (PMID 37108185, 2023). "Moreover, hypoxia, a common condition essential for tumor metastasis, stimulates the expression of transcription factor hypoxia-inducible factor 1 (HIF-1) in tumor cells and activates many genes of proteases, including MMP-9." (PMID 37175113, 2023). "In addition, the nanoprobe‐based quantitative imaging also revealed that the invasion directions of tumour cells during the tumour development process is also closely related with the pH variation and MMP‐9 expression." (PMID 38264683, 2023). "The findings of this study suggested that MMP9 was highly expressed in NSCLC tumor tissues." (PMID 37978381, 2023). "This study yields new insights into the key components of the residual tumor bed, such as MMP-9, which is strictly associated with the lack of a pathological response to NAC." (PMID 37511057, 2023). "MMP-9 is important in promoting the extravasation of tumor cells in TME." (PMID 37766868, 2023). "CD9+MMP9+MMP2-TIMP1- and MMP9+MMP2-TIMP1+ subpopulations of circulating sEVs are the most promising predictors of the efficacy of thermoradiation therapy because their levels at baseline differ significantly in CRCPs with different tumor responses." (PMID 37109070, 2023). "A large amount of active MMP-2 and MMP-9 was found in tumor tissues." (PMID 36674771, 2023). "Through decreasing both endogenous and PMA-induced MMP-9 expression, wogonin could inhibit tumor invasion and metastasis." (PMID 36831555, 2023). "In addition, co-treatment of CSRM617 and OCT attenuated the expression of ki-67 and MMP9 on tumor tissues, which indicated the significant suppression of tumor cell proliferation and invasion activity." (PMID 37444485, 2023). "Therefore, the combination of GM‐CSF neutralization and MMP9 inhibition can synergistically reduce angiogenesis and tumor progression." (PMID 36560848, 2023).
tumor (continued). "Previous works have demonstrated N‐glycosylation of CD147 mediated by GNT-V has the high activity to stimulate the production of MMP-2 and MMP-9, thus lead to degradation of type IV collagen and promoted tumor cell invasion and metastasis in multiple types of cancer." (PMID 36594096, 2023). "The gene expression of TIMP1, MMP2 and MMP9 has been assessed in tumor tissue and blood." (PMID 37509417, 2023). "Immunohistochemical analysis showed that TIMP1/MMP9/CD44 ternary complex expression in primary tumor avatars paralleled an increase of the expression levels of TWIST, SNAIL in the xenograft metastasis, resembling the phenotypic landscape of PTC and ATC patient-derived primary and metastatic lesions." (PMID 36906579, 2023). "In addition, MMP2 and MMP9 are well known to be involved in metastases and tumor cell dissemination of several tumors." (PMID 37240283, 2023). "Moreover, both TERT deficiency and dysfunctional telomeres decreased lung tumor implantation and expression of the tumor progression markers Mmp9, Egfr, Hmox1 and c-MET." (PMID 37085672, 2023). "Additionally, research has demonstrated that APOJ stimulates colon cancer metastasis and tumor invasion via the p38/MAPK/MMP9 pathway." (PMID 38067270, 2023). "Without differentiation of the tumor subtypes, it has been shown that higher MMP9 expression is associated with shorter survival in NSCLC patients." (PMID 37509417, 2023). "Moreover, NAMI-A has been proposed to reduce invadopodia in tumor cells where MMP-9 is preferentially localized in active form and decrease the secretion of MMP-9." (PMID 36674771, 2023). "isolated Tregs from the peripheral blood of eight healthy volunteers and then cocultured them with the human NSCLC cell line 95 D. The results showed that matrix metalloproteinase-9 (MMP-9) expression in tumor cells was increased and apoptosis was decreased following coculture with Tregs." (PMID 36776832, 2023). "Other neutrophil-derived factors, such as granules containing neutrophil elastase (NE), neutrophil collagenase (or MMP8), and gelatinase B (or MMP9) can remodel the ECM in the TME or act directly on tumor cells themselves to boost tumor proliferation and invasion." (PMID 37398649, 2023). "Immunohistochemical determination of Ki67 and MMP-9 protein expression showed that ZBSO could inhibit tumor proliferation and invasion." (PMID 37081962, 2023). "In summary, the LCN2/LOXL2/MMP9 ternary complex promoted the migration and invasion of cancer cells and malignant tumour progression through multiple mechanisms and could be a potential therapeutic target." (PMID 37753805, 2023). "Epstein–Barr virus oncoprotein induces MMP-9 expression, which may contribute to tumor invasion and metastasis." (PMID 37447286, 2023). "MMP-2 and MMP-9 belong to gelatinases that, by degrading type IV collagen in the basement membrane, can contribute to carcinogenesis processes, such as cell proliferation, angiogenesis, and tumor metastasis when their activity is dysregulated." (PMID 37445754, 2023). "However, along with tumor diameter and positive nodal status at diagnosis, matrix metalloproteinase-9 (MMP-9) expression in the residual TME was identified as an independent factor associated with the impaired response to NAC." (PMID 37511057, 2023). "Furthermore, NAP1L2 cooperated with YY1 to promote the transcription of MMP2 and MMP9, which promoted tumor metastasis." (PMID 36195720, 2023). "The MMP-9 expression in tumor tissues was downregulated with an inhibitory greater than that of oxaliplatin, which could be ascribed to the incorporation of the naproxen ligand." (PMID 36674771, 2023). "Literature shows the involvement of MMP-9 in tumor angiogenesis." (PMID 36674806, 2023).
tumor (continued). "It targets AMPK (Adenosine monophosphate activated protein kinase) and mTOR (mammalian or mechanistic target of rapamycin) molecule signaling pathways by modulating NF-κB, MMP-2 (matrix metalloproteinase-2), and MMP-9 (matrix metallopeptidase 9) proteins to regulate tumor formation." (PMID 36677808, 2023). "In addition, VEGF and TNF production from N2 TANs promote tumor vascularization and Matrix Metalloproteinases (MMP)-9 secretion, which participates in the tumor extracellular matrix reconstruction and contributes to subsequent tumor metastasis." (PMID 37063873, 2023). "MMP9 can regulate the immune infiltration in ccRCC and affect tumor progression." (PMID 36959648, 2023). "MMP-9 as an important proteolytic enzyme is expressed multiple tumors and enhances cell invasion and metastasis abilities by degrading extracellular matrix, thus facilitating tumor cell invasion and migration." (PMID 37100467, 2023). "NOS2 facilitates tumour cell angiogenesis, invasion, and metastasis through upregulating MMP9." (PMID 37795447, 2023). "It seems that tumor cells hijack the BMSCs and make them produce MMP-9." (PMID 36674806, 2023). "In addition, macrophage-derived TGF-β1 enhances the aggressiveness of tumour cells in a mouse model by promoting expression of MMP-9 and increasing the aggressiveness of tumour cells." (PMID 38143746, 2023). "Producing MMP-9 from cancer cells relies on several growth factors and cytokines, which involve the mitogen-activated protein kinases (MAPK) signalling pathway and have been implicated in tumour progression and its spreading." (PMID 37600570, 2023). "Importantly, collagen IV peptides resulting from MMP-2 and MMP-9 mediated cleavage chemoattract BMDCs and circulating tumor cells (CTCs) to PMNs and promote metastasis." (PMID 37350937, 2023). "The inhibition of tumor growth could be attributed to a decrease in extracellular matrix degradation resulting from the downregulation of MMP9 expression." (PMID 37963919, 2023). "Furthermore, other natural products, such as curcumin, quercetin, and polyphenol, inhibit MMP-2 and MMP-9 expressions and tumor metastasis." (PMID 37700002, 2023). "Although IL-17 enhances synoviocyte invasion in a hypoxic environment by upregulating MMP2 and MMP9, its function in tumor cells in a hypoxic environment is yet unknown." (PMID 37064125, 2023). "Blocking MMP2/MMP9 and TGFβ thereby can reduce tumor growth." (PMID 37376417, 2023). "Consequently, the delivery system successfully downregulated pro-tumor factors, including IL-10, MMP9, and VEGF, but upregulated anti-tumor factors like IL-12 in TAMs." (PMID 38258072, 2023). "Furthermore, neutrophil can stimulate dormant cancer cells through release of MMP9 which can produce epitopes that bind to tumor integrins and trigger the proliferation of cancer cells." (PMID 36609243, 2023). "Moreover, high expression of MMP-2 and MMP-9 was observed in Salmonella-infected tumor tissues, while E-cadherin expression was attenuated in tumor tissues." (PMID 36812247, 2023). "HIF-2 selective or co-regulated target genes associated with tumor growth and metastasis (VEGFa, PAI1, MMP9, GLUT1) were induced in acetylation-intact (K3) HIF-2α and nuclear-localizable (WT) Acss2 knockdown/rescue cells under hypoxia and low glucose conditions." (PMID 36862715, 2023). "CCL5 directly induce TAMs to secrete MMP9 and promote tumor cell metastasis." (PMID 37141250, 2023). "Among them, MMP9 was associated with macrophage M0 in 12 tumor types, PTGS2 was associated with six immune cell types among six tumor types, and TNF with seven immune cell types in five tumor types." (PMID 37033970, 2023). "These enzymes, such as matrix metalloproteinases (MMPs), can be expressed by tumoral cells in the tumor itself, It has been observed that MMP9, is one of the most important proteolytic enzymes in ECM remodeling in various types of cancers." (PMID 37153807, 2023).